IL10 (interleukin 10)
Diseases named in the same sentence as IL10 in open-access papers (continued):
Sharing a sentence is not in itself a finding about the gene and the disease.
endometriosis (continued). "Nevertheless, contradictory results for levels of IL-10, IL-1β, IL-2 and TNF-α in the peritoneal fluid of women with endometriosis has been also reported." (PMID 34639133, 2021). "Increased amounts of prostaglandins, activated macrophages, IL-1, IL-6, IL-10, and tumor necrosis factor alpha (TNF-α) have been found in the PF of patients with endometriosis when compared to the PF of control groups." (PMID 34900746, 2021). "Concentrations of IL-6, IL-10, CCL2, CXCL8 and CXCL9 were significantly upregulated in the PF from women with endometriosis when compared to control women, whereas concentrations of other cytokines and chemokines were unaffected." (PMID 34360900, 2021). "The levels of some investigated cytokines and chemokines, such as IL-6, IL-10, CCL2, CXCL8, and CXCL9, were significantly increased in PF from patients with endometriosis as compared to control." (PMID 34360900, 2021). "Differential expression of antiinflammatory cytokines (IL-10, TGF-β, TLR4 and NF-κB) occurs in women with endometriosis, and this can promote survival, growth, invasion, differentiation, angiogenesis, and immune escape of the endometriotic lesions." (PMID 32210799, 2020). "They found that IL-6, IL-10, IL-13, and TNF-α are highly expressed in the peritoneal fluid of endometriosis patients." (PMID 33354460, 2020). "MYD88, NF-ĸB, IL-10, and TGF-β showed a significantly higher expression in endometriosis patients compared to the control (p<0.05)." (PMID 33209739, 2020). "We further explored the infiltration of pDCs, the expression of IL‐10/IL‐10R, and the density of CD31+ blood vessel cells in human endometrioma lesions from patients with stage III or IV endometriosis." (PMID 31418859, 2019). "Monocyte-derived dendritic cells that were conditioned with serum from women with endometriosis displayed a tolerogenic phenotype, including downregulation of CD86 and HLA-DR, as well as increased IL-10 but decreased IL-12 production." (PMID 30276219, 2018). "Previous studies showed that serum of women with endometriosis had higher concentrations of IL-10, TNF-α, and TGF-β, and administration of these cytokines, such as IL-10, promoted the growth of endometriotic lesions in a murine model." (PMID 30276219, 2018). "IL-27 inhibits Th17 differentiation, and promotes the production of IL-10 in Th17 cells by the c-Maf/RORC/Blimp-1 complex, participating in the formation of an immune tolerance pattern in the late stage of endometriosis." (PMID 28300844, 2017). "In contrast to endometriosis, ovarian malignancies are characterized by elevated peritoneal fluid concentrations of IL-10 and TNF-alpha, elevated serum concentrations of IL-10 and low serum levels of TNF-alpha." (PMID 28376925, 2017). "Consistent with our in vitro results, blocking TECK resulted in a marked decrease in Treg differentiation, and decreased the expression of IL-10, TGF-β and CD73 by Tregs in endometriosis lesions." (PMID 25275597, 2014). "Platelets and other inhibitory cytokines, IL-6, IL-16, IL-17, IL-1β, IL-10, and TGF-β, are found in the peritoneal fluid in patients with endometriosis and function to prevent the NK cells from degranulation and producing interferon (IFN)-γ, impairing the NK cell function." (PMID 40747182, 2025). "All endometriosis forms share core immunopathogenetic mechanisms: macrophage accumulation with M2 polarization, reduced NK cytotoxicity, elevated pro-inflammatory cytokines (IL-1β, IL-6, TNF-α) alongside immunosuppressive mediators (IL-10, TGF-β)." (PMID 41488658, 2025). "The enrichment of genes such as IL10 and HBEGF in network toxicology analysis suggests that PFAS may contribute to endometriosis by disrupting immune tolerance mechanisms." (PMID 41492385, 2025). "Furthermore, the study suggested that women with endometriosis-related infertility presented increased levels of TNF-α, IL-1, IL-6, IL-10, TGF-β1, and IL-8 in peritoneal fluids." (PMID 38813329, 2024).
endometriosis (continued). "constructed the co-culture systems of NK cells, macrophages, and ESCs from patients with endometriosis and discovered that the expression of CD16, NKG2D, perforin, and IFN-γ was significantly downregulated, while the secretion of IL-1β, IL-10, and TGF-β was increased." (PMID 36865552, 2023). "Indeed, in endometriotic lesions, the levels of IFN-γ and IL10 and the ratios of IL4/IFN-γ, IL4/IL2 IL10/IFN-γ, and IL10/IL2 are significantly elevated in the peritoneal fluid of endometriosis patients compared to healthy controls." (PMID 35935991, 2022). "Furthermore, the PF from women with endometriosis also contains increased levels of suppressive anti-inflammatory cytokines such as TGF-β and IL-10." (PMID 34360900, 2021). "A higher percentage of FoxP3 Tregs, and immunosuppressive cytokines, interleukin-10 (IL-10), transforming growth factor beta (TGF-β) levels are present in the PF and increased expression in endometriotic tissue of patients with endometriosis compared to control women." (PMID 34900746, 2021). "Higher levels of IL-10 and TGF-β, two key cytokines responsible for regulating the proliferation and activity of Tregs, were found in the peritoneal fluid and serum of patients with endometriosis than in normal controls." (PMID 32676072, 2020). "Thus, these inflammatory factors (IL-6, IL-10, IL-13, and TNF-α) can be used as essential reference indexes for endometriosis diagnosis complicated with infertility." (PMID 33354460, 2020). "M0s, proinflammatory macrophages [M(LPS+IFN-γ)], prorepair macrophages [M(TGF-β + IL-10 + IL-4)], and macrophages activated with PF from women without endometriosis [M(No Endo)] were included for comparison." (PMID 31291762, 2019). "Similarly, after preincubation with SB43154, the mRNA expression levels of CD163 and IL-10 were decreased while CD86 and IL-12 expression was increased in macrophages treated with serum from endometriosis patients." (PMID 30276219, 2018). "A significant increase in IL-10 levels was also observed in peritoneal fluid from women with endometriosis of stage III–IV while there was no statistical difference in IL-10 concentration between healthy controls and women with endometriosis at stage I–II." (PMID 25275597, 2014). "Endometriosis-related CCC is thought to be a chronic inflammatory disease, characterized by increased production of pro-inflammatory cytokines such as IL-1, IL-6, IL-8, IL-10, and TNF-α." (PMID 25366985, 2014). "Significantly higher IL-6 and IL-10 levels were found in moderate-to-severe but not in minimal-to-mild endometriosis as compared to controls." (PMID 23843796, 2013). "Patients with endometriosis exhibit systemic monocyte activation: their spontaneous and induced production of proinflammatory cytokines TNF-α, IL-6, and IL-8 is elevated with normal levels of anti-inflammatory IL-10, indicating a proactive state of the monocyte-macrophage system." (PMID 41488658, 2025). "Meanwhile, the concentrations of immunosuppressive cytokines such as IL-4, IL-10, and TGF-β, which have been reported to participate in the pathogenesis of the disease through immune escape and the survival of ESCs, are also increased in the PF of patients with endometriosis." (PMID 36865552, 2023). "It should be stressed, however, that increased concentrations of IL-10 in the peritoneal fluid of women with endometriosis may not necessarily be a sole effect of increased proportions of Treg cells." (PMID 34501240, 2021). "The first one is that we could not provide evidence showing the role of IL‐10‐expressing pDCs during the adherence stage using the surgery‐induced endometriosis model, as the endometrial tissue was forcedly sutured into the peritoneal cavity in the mouse." (PMID 31418859, 2019). "Under this tight regulation, it is unclear whether shed endometrium can secrete IL‐10 protein or not in the early stage of endometriosis." (PMID 31418859, 2019).
endometriosis (continued). "However, in addition to immune suppression, the role of IL‐10 in the development of endometriosis has not been well studied, especially its angiogenic activity in the endometriotic microenvironment." (PMID 31418859, 2019). "Administration with anti-mouse IL-10 neutralizing Abs or TGF-β receptor antagonist (SB431542) also limited the growth of endometriosis lesions and downregulated the expression of Ki67, MMP2 and Cox-2 by ESCs and endometrial glandular epithelial cells (EECs) in the endometriosis lesions." (PMID 25275597, 2014). "The increased levels of IL-10 and TGF-β produced by Tregs in response to TECK and other cell types (such as ESCs and macrophages) may further modulate the progression of endometriosis through anti-inflammatory pathways and directly enhance the biological behavior of ESCs in the peritoneal cavity." (PMID 25275597, 2014). "In addition, the expression levels of CD163 mRNA and CD86 mRNA as well as cytokine IL-10 mRNA were not significantly different between the two groups, whereas the expression of IL-12 mRNA in the peritoneal macrophages of endometriosis patients was decreased, as compared with that in control samples." (PMID 30276219, 2018). "Analysis of biomarkers IL-8, IL-10, BDNF, and VEGF-A was conducted in both the endometriosis group and the control group with non-endometriotic gynecological pathology." (PMID 39202309, 2024). "In our study, the analysis of the correlations regarding Ucn1 serum concentrations and cytokines levels including IL-2, IL-4, IL-6, IL-10 and IFN-gamma also brought not so many significant dependencies among women with endometriosis and healthy controls." (PMID 37175494, 2023). "We found elevated levels of HO-1 along with IL-10 and the pro-inflammatory cytokines (IL-1β, IL-16, IFNγ) in PM but not in PBMC from endometriosis patients." (PMID 35565370, 2022). "However, there are studies that have shown that the serum levels of IL-10, TNF-alpha, and soluble HLA-G (sHLA-G) alone are not sufficient for differentiating between endometriosis and cancer, despite being significantly increased compared to their levels in benign lesions." (PMID 38337827, 2024). "Furthermore, IL-10 and TGF-β mRNA expression were significantly higher in ectopic lesions than eutopic endometrium from women with or without endometriosis, particularly in cases of advanced endometriosis." (PMID 32676072, 2020).
endotoxemia (101 papers, 2008 to 2026). "Biliverdin treatment resulted in increased survival of rats submitted to a model of endotoxemia by LPS injection, which was associated with milder lung inflammation, decreased systemic IL-6 levels and enhanced IL-10 secretion by macrophages." (PMID 33266044, 2020). "It was suggested that chronic endotoxemia is associated with increased plasma IL-10 levels in cirrhotic patients." (PMID 27861595, 2016). "We hypothesize that the lower production of pro-inflammatory cytokines at CT0 is due to high levels of IL-10, which spikes earlier during endotoxemia due to the loss of REV-ERB." (PMID 33788832, 2021). "TLR4-mediated and CD40-mediated signals received by macrophages during early endotoxemia are known to promote IL-10 transcription, which can in turn signal to degrade mRNA encoding TNFα, thus identifying IL-10 as a crucial feedback control molecule that mediates cessation of inflammation." (PMID 27125280, 2016). "As a well-known anti-inflammatory cytokine, IL-10 can potentiate systemic inflammation in humans with experimental endotoxemia and increase NK-derived IFN-γ production in psoriatic patients." (PMID 39656009, 2025). "Cmtm3 KO alleviated the release of TNF-α, IL-1β, and IL-10 in the peripheral blood of LPS-induced endotoxemia mice, while TLR4 overexpression reversed this alleviating effect." (PMID 39455728, 2024). "In this study, there was a clear increase, over time, in TNF-α, IL-6, and IL-10 in both experimental groups, which is characteristic and consistent with the correct induction of endotoxemia." (PMID 38338117, 2024). "We also analyzed cytokine levels in plasma and detected a strong release of tumor necrosis factor, interleukin-6 (IL-6), monocyte chemoattractant protein-1, and IL-10 48 h after endotoxemia." (PMID 38984201, 2024). "Surprisingly, endotoxemia-induced IL-10 release was attenuated following atazanavir-induced hyperbilirubinemia." (PMID 37261364, 2023). "In conclusion, the present study is the first to demonstrate that hyperbilirubinemia elicited by atazanavir improves the anti-oxidant status, reduces IL-10 release, and prevents vascular hyporeactivity during experimental endotoxemia in humans." (PMID 37261364, 2023). "Differential regulation of IL-6 and IL-10 responses to splanchnic nerve denervation aligns with our recent findings in rodent endotoxemia." (PMID 37535121, 2023). "Atazanavir-induced hyperbilirubinemia increases antioxidant capacity, attenuates interleukin-10 release, and prevents vascular hyporesponsiveness during human systemic inflammation elicited by experimental endotoxemia." (PMID 37261364, 2023). "In this context, administration of exogenous IL-10 to mice and human patients showed potent inhibitory effects on the development of inflammation resulting from endotoxemia." (PMID 35464430, 2022). "This potential pro-inflammatory promoting character of IL-10 has already been observed during human endotoxemia." (PMID 35464430, 2022). "In LPS-mediated endotoxemia, Il-10 is well-known to exert an immunoregulatory function, and mice lacking Il-10 production showed increased lethality in response to LPS." (PMID 34502552, 2021). "The importance of Il-10 in maintaining survival during endotoxemia was shown by Il-10 knockout animals and Il-10 injections." (PMID 34502552, 2021). "Genetic deletion of Cdk5 in myeloid cells increases c-Maf and hence Il-10 levels during LPS-induced endotoxemia, contributing to reduced lung inflammation and increased survival." (PMID 34502552, 2021). "Previous studies showed that total p35 KO mice have an ameliorated colitis in the dextran sulfate sodium model and a reduced disease severity in an endotoxemia model through enhanced production of Il-10." (PMID 34502552, 2021). "Mice lacking Cdk5 in macrophages (Cdk5LysMcre) show increased pulmonary c-Maf, Il-10, and plasma Il-10 levels in a model of LPS-induced endotoxemia, resulting in improved disease severity and survival." (PMID 34502552, 2021).
endotoxemia (continued). "Together, these results suggest that the deletion of Cdk5 in macrophages increases c-Maf expression in the lung tissue and thus induces the expression of the anti-inflammatory cytokine Il-10 during LPS-induced endotoxemia." (PMID 34502552, 2021). "Endotoxemia triggers strong pro-inflammatory responses (mediated by IL-12p40) that are balanced by anti-inflammatory IL-10 cytokine." (PMID 32178295, 2020). "We examined serum concentrations of IL-1β, IL-6, TNF-α, and IL-10 to investigate the effect of BAFF antibody on systemic inflammation in endotoxemia." (PMID 33324396, 2020). "In conclusion, even with elevated endotoxemia, individuals with High VO2max exhibited higher IL-6 concentration in peripheral blood post-acute aerobic exercise and lower IL-10 concentration during recovery (1 h post-exercise)." (PMID 32839476, 2020). "We have previously reported that chitohexaose produced IL-10 in both human monocytes and mouse bone marrow derived macrophages and protected mice against LPS-induced endotoxemia." (PMID 30814582, 2019). "Studies have suggested that IL-10 protects against lethality during endotoxemia-induced shock in mice." (PMID 30200495, 2018). "Endotoxemia is known to increase pro-and anti-inflammatory cytokines in mice and human, in particular IL-10, IL-6, and TNF-α34." (PMID 29269852, 2017). "IL-10 has also been proven to be essential in preventing lethal endotoxic shock because depletion of IL-10 resulted in increased mortality in an endotoxemia model." (PMID 28482922, 2017). "Hemoadsorption therapy with a clinically approved device (CytoSorbTM) removes cytokines (interleukin-6, interleukin-10, and tumor necrosis factor, amongst others) and improves short-term survival in a rat model of endotoxemia." (PMID 28779451, 2017). "We have shown previously that chitohexaose, a small molecule of nematode origin, mediates TLR4-dependent M2 activation of macrophages with prominent IL-10 production and blocks LPS-mediated endotoxemia." (PMID 27125280, 2016). "In an experimental model, it was shown that the administration of recombinant murine IL-10 protects from lethal endotoxemia, even when IL-10 was injected 30 minutes after LPS administration." (PMID 25614712, 2014). "Emerging evidence also suggests that IL-10 plays a major role in suppressing endothelial dysfunction in lipopolysaccharide (LPS)-induced endotoxemia." (PMID 25387998, 2014). "In contrast, the immunoneutralization of IL-10 led to elevated levels of circulating TNF-α and IL-6 in mice and reversed the ability of IL-10 to protect mice from lethal endotoxemia." (PMID 23853427, 2013). "In an experimental murine model, the administration of recombinant IL-10 protein protected mice from lethal endotoxemia, even when IL-10 was injected 30 minutes after the LPS administration." (PMID 23853427, 2013). "The major source of circulating IL-10 in endotoxemia and abdominal infections are presumably Kupffer cells which are exposed to gut-derived LPS via the portal vein." (PMID 23446058, 2013). "In these studies, the reduced release of cytokines such as TNF-α, IL-1β, and IL-10 was quite dramatic in an endotoxemia model." (PMID 23109904, 2012). "Anti-inflammatory cytokines such as IL-10 are also produced during endotoxemia, which can down-regulate the production of proinflammatory cytokines and provide a key mechanism for limiting the inflammatory response in the lungs." (PMID 23024464, 2012). "Myeloid-specific TAK1 deficiency in mice leads to increased levels of circulating IL-1β, TNF and reduced IL-10 after LPS challenge and sensitizes them to LPS-induced endotoxemia." (PMID 22348103, 2012). "In accordance, administration of IL-10 protects mice from lethal endotoxemia, and IL-10 knockout mice have a more-pronounced hemodynamic response to LPS administration." (PMID 22129171, 2011). "In our study, treatment with dipyridamole profoundly enhanced the antiinflammatory IL-10 response during endotoxemia." (PMID 22129171, 2011).